MELK (maternal embryonic leucine zipper kinase)
Description:
Serine/threonine-protein kinase involved in various processes such as cell cycle regulation, self-renewal of stem cells, apoptosis and splicing regulation. Has a broad substrate specificity; phosphorylates BCL2L14, CDC25B, MAP3K5/ASK1 and ZNF622. Acts as an activator of apoptosis by phosphorylating and activating MAP3K5/ASK1. Acts as a regulator of cell cycle, notably by mediating phosphorylation of CDC25B, promoting localization of CDC25B to the centrosome and the spindle poles during mitosis. Plays a key role in cell proliferation and carcinogenesis. Required for proliferation of embryonic and postnatal multipotent neural progenitors. Phosphorylates and inhibits BCL2L14, possibly leading to affect mammary carcinogenesis by mediating inhibition of the pro-apoptotic function of BCL2L14. Also involved in the inhibition of spliceosome assembly during mitosis by phosphorylating ZNF622, thereby contributing to its redirection to the nucleus. May also play a role in primitive hematopoiesis.
Synonyms: hPK38; KIAA0175
Tractability: Small molecule: a structure with a bound ligand is known; a high-quality ligand is known; it belongs to a druggable protein family. Antibody: UniProt places it where antibodies can reach, with high confidence; its Gene Ontology location is reachable by antibodies, with high confidence. PROTAC: it is named in the literature on targeted protein degradation; ubiquitination databases record sites on it; a small molecule that binds it is known.
Target class: CAMK protein kinase MELK subfamily; Protein Kinase; CAMK protein kinase CAMK1 family; Enzyme; Kinase; CAMK protein kinase group
Chemical probes: JNJ-47117096 (high quality), NVS-MELK8a (high quality), OTSSP167
Gene: Protein-coding gene on chromosome 9 (36,572,074 to 36,682,131, forward strand). Ensembl gene ENSG00000165304.
Subcellular location: Cell membrane
Gene Ontology:
Molecular function: calcium ion binding; non-membrane spanning protein tyrosine kinase activity; protein binding; protein serine/threonine kinase activity; ATP binding; protein kinase activity; protein serine kinase activity; protein tyrosine kinase activity
Biological process: apoptotic process; cell population proliferation; protein autophosphorylation; G2/M transition of mitotic cell cycle; hemopoiesis; neural precursor cell proliferation; positive regulation of apoptotic process
Cellular component: cell cortex; membrane; plasma membrane; cytoplasm
Genetic constraint (gnomAD): Loss-of-function variants: 45 observed, 52.54 expected, observed/expected ratio (o/e) 0.86, 90% interval 0.67 to 1.1. The upper end of that interval is the gene's LOEUF score, 1.1, which puts it in group 4 of 6, group 1 being the genes least tolerant of losing a copy. Missense variants: 574 observed, 619.13 expected, observed/expected ratio (o/e) 0.93, 90% interval 0.87 to 0.99. Synonymous variants: 202 observed, 221.4 expected, observed/expected ratio (o/e) 0.91, 90% interval 0.81 to 1.02.
Homologues: Orthologues: chimpanzee MELK (99% identical), macaque MELK (98% identical), dog MELK (92% identical), pig MELK (91% identical), rabbit MELK (91% identical), guinea pig MELK (88% identical), rat Melk (83% identical), mouse Melk (83% identical), tropical clawed frog melk (65% identical), zebrafish melk (58% identical), Caenorhabditis elegans pig-1 (40% identical). Paralogues in human: BRSK2 (27% identical), BRSK1 (26% identical), PRKAA1 (25% identical), SIK2 (25% identical), PRKAA2 (25% identical), SIK3 (25% identical), SIK1 (24% identical), SNRK (24% identical), NUAK2 (23% identical), NUAK1 (23% identical), HUNK (22% identical), NIM1K (18% identical), and 5 more.
Diseases named in the same sentence as MELK in open-access papers:
MELK is named in the same sentence as 111 diseases in open-access papers, as found by Europe PMC text mining. Sharing a sentence is not in itself a finding about the gene and the disease. The quoted sentences say what the papers report.
breast carcinoma (73 papers, 2007 to 2025). "So, here, we have shown that genes co-expressed with MELK in breast cancer tumors have previously been implicated in metastasis." (PMID 40076867, 2025). "To explore potential mechanisms underlying the association between MELK expression and poor prognosis, we analyzed the transcriptomic profiles of primary breast cancer tumors from the TCGA-BRCA database (n = 1111)." (PMID 40076867, 2025). "MELK is frequently upregulated in basal-like breast cancer compared with the other subtypes of breast cancer, and elevated MELK expression in breast cancer tissue is associated with shorter patient survival." (PMID 37377604, 2023). "High MELK expression has been associated with immune cell infiltration and pathologic complete response after neoadjuvant chemotherapy in breast cancer." (PMID 37377604, 2023). "We found that high MELK expression was associated with worse outcomes in patients with breast cancer." (PMID 37377604, 2023). "Collectively, our findings confirm that MELK expression is significantly upregulated in aggressive breast cancer and is associated with the gain of gene copies as the main alteration." (PMID 35749404, 2022). "Our data suggest that overexpression and CN gains of MELK can be developed as a diagnostic and prognostic marker to identify patients who have more aggressive breast cancer." (PMID 35749404, 2022). "Collectively, these findings suggest that MELK expression is upregulated in breast cancer, especially in TNBC, and is a promising diagnostic and therapeutic modality." (PMID 34285339, 2021). "Based on integrated bioinformatic analysis, the present study has identified 321 DEGs and six hub genes (CDK1, CCNA2, TOP2A, CCNB1, KIF11, and MELK) that are associated with breast cancer tumorigenesis and progression." (PMID 31428132, 2019). "Of note, the high overexpression of MELK in most of the comparisons is likely due to effects unrelated to the apoptotic pathway, since this gene encodes an oncogenic kinase in breast cancer." (PMID 31825969, 2019). "HTH-01-091 is cell permeable, causes MELK degradation, but demonstrates poor antiproliferative effects in basal-like breast cancer cell lines." (PMID 28926338, 2017). "Another study also showed that DEPDC1 is associated with the antitumor activity of MELK (maternal embryonic leucine zipper kinase) inhibitor in breast cancer cells." (PMID 28969015, 2017). "In multiple independent breast cancer cohorts analyzed, we found a strong association of high expression levels of MELK with a higher grade of malignancy and an unfavorable prognosis regardless of the treatment modality." (PMID 24844244, 2014). "While high MELK expression seems to be a unique phenomenon for BBC in breast cancer, MELK overexpression has been associated with tumor aggressiveness and poor outcome in a number of other cancer types, including glioblastoma, astrocytoma, and prostate cancer." (PMID 24844244, 2014). "MELK is a recently identified protein kinase and candidate oncoprotein that is upregulated in several types of cancer, including breast cancer, and is associated with resistance to apoptosis." (PMID 19671159, 2009). "Because high MELK expression was associated with a high risk of death and short OS in patients with breast cancer, we hypothesized that MELK promotes the growth of human breast cancer cells." (PMID 37377604, 2023). "The evidence provided by this study supported the instance that the PCDHB17P/miR-145-3p/MELK/NF-κB axis is implicated in the metastasis and angiogenesis of breast cancer and may be considered as a potential target for the breast cancer therapies in the future." (PMID 34350110, 2021). "MELK is also associated with poor patient survival in breast cancer." (PMID 34350110, 2021).
breast carcinoma (continued). "We therefore tested whether loss of MELK impairs mammosphere formation, a phenotype tightly linked with breast cancer stem cell activity." (PMID 29417930, 2018). "MELK has previously been implicated in the maintenance of breast cancer stem cells." (PMID 29417930, 2018). "Among MELK-associated cancers, breast cancer is one of particular interest." (PMID 28926338, 2017). "Other reports implicated that MELK could play essential roles in maintenance of CSCs for breast cancer and glioblastoma cells, and therefore be an attractive target to eradicate CSCs." (PMID 26871945, 2016). "Furthermore, MELK is associated with anti-apoptotic activities of breast cancer cells by interacting with Bcl-G, a pro-apoptotic member of the Bcl-2 family." (PMID 24185907, 2013). "Increased MELK expression is associated with poor prognosis in breast cancer." (PMID 24167714, 2013). "In addition, MELK expression is increased in breast cancer tissue and this increase is also associated with poor patient survival, as predicted for a candidate oncogene." (PMID 19671159, 2009). "More recently, GR activation has been observed in breast cancer metastases and was associated with a GR activation signature which included genes such as MELK, CDK1, and particularly the ROR1 kinase, which may mediate resistance to chemotherapeutic agents and increase colonization." (PMID 31675993, 2019). "In addition, several studies have demonstrated that high expression of MELK was correlated with poorly differentiated phenotypes (malignancy grade) in human astrocytoma and prostate cancers, and is associated with poor prognosis of breast cancer patients." (PMID 26871945, 2016). "Moreover, high levels of MELK expression correlated with poorly differentiated histological types of brain tumor and prostate cancer, and is associated with poor prognosis of patients with breast cancer." (PMID 25365263, 2014). "We evaluated the role of MELK in breast cancer stem cell properties using a mammosphere formation assay in MDA-MB-231 cells, a high-MELK-expressing cell line." (PMID 40076867, 2025). "Collectively, these results demonstrate that MELK inhibition impairs migration efficiency in vitro in high-MELK-expressing breast cancer cell lines." (PMID 40076867, 2025). "MELK is a serine/threonine kinase that is overexpressed in multiple malignancies, including breast cancer, where its expression is particularly high in TNBC compared to ER-positive subtypes." (PMID 40076867, 2025). "Collectively, these results from two distinct cell line models strongly indicate that MELK overexpression enhances metastatic potential in breast cancer." (PMID 40076867, 2025). "MELK has also been shown to influence radiation and chemotherapy response and is an important determiner of intrinsic breast cancer subtype." (PMID 40076867, 2025). "We used a mammosphere formation assay to assess the role of MELK in stem cell properties in breast cancer." (PMID 40076867, 2025). "We examined the contribution of MELK to the induction of EMT in breast cancer cells by determining the impact of MELK knockdown or inhibition on the expression of epithelial and mesenchymal markers using Western blot analysis." (PMID 37377604, 2023). "Recently, an analysis of The Cancer Genome Atlas data showed that MELK is in the top 1% of overexpressed genes in breast cancer, and its expression is eight times as high in breast tumors as in normal breast tissues." (PMID 37377604, 2023). "Overall survival analysis of NUSAP1, MELK, and CDK1 in breast cancer patients has provided valuable insights into the underlying mechanisms of tumor progression." (PMID 38084295, 2023). "Our gene expression profile studies showed that MELK mRNA expression was highly elevated in TNBC and that high MELK mRNA expression was associated with a high risk of death in patients with breast cancer." (PMID 37377604, 2023).
breast carcinoma (continued). "In univariate analysis, patients with breast cancer with high-MELK–expressing tumors had worse overall survival (P < 0.001) and distant metastasis-free survival (P < 0.01) than patients with low-MELK–expressing tumors." (PMID 37377604, 2023). "Previous studies have found that CENPF, MELK, PBK, TOP2A and NEK2 are upregulated in breast cancer and this is associated with a poor prognosis." (PMID 36776306, 2023). "Like MELK, NUSAP1 is a protein kinase that promotes cell proliferation and survival, and its overexpression in breast cancer patients has been linked to a poor prognosis." (PMID 38084295, 2023). "MELK mRNA expression is highly up-regulated in basal-like breast cancer (BLBC), the major molecular subtype of TNBC, compared to luminal or other subtypes of breast tumors." (PMID 35749404, 2022). "In this study, we have shown that MELK expression is highly increased in BLBC compared to other subtypes of breast cancer from AA-enriched women." (PMID 35749404, 2022). "To test the possibility for MELK to be developed as breast cancer prognostic marker, we conducted IHC in 87 human breast tissue samples: IDC (n = 39), ductal carcinoma in situ (DCIS) (n = 10), metastases to lymph nodes (n = 5), and benign (n = 33)." (PMID 35749404, 2022). "We found that MELK protein in either nuclear, or cytoplasmic, or combined nuclear+/cytoplasmic+ compartments was significantly higher in IDC compared with benign tissues, suggesting the important role of MELK in the occurrence and progression of breast cancer." (PMID 35749404, 2022). "Analyses of MELK CNA and gene expression data revealed that MELK expression was also significantly correlated with CN across breast cancer cell lines (r = 0.52, p < 0.001) as well as across all cell lines of female cancers (r = 0.49; p < 0.001)." (PMID 35749404, 2022). "To evaluate molecular markers of MELK aberrations in aggressive breast cancer, we assessed MELK gene amplification and expression in breast tumors." (PMID 35749404, 2022). "We next determined MELK expression in breast cancer cell lines using Cancer Cell Line Encyclopedia (CCLE) databases, which showed a significant increase in MELK mRNA in BLBC cell lines compared to other subtype cells (p = 0.04)." (PMID 35749404, 2022). "TCGA breast cancer dataset demonstrated a moderate and significant increase in MELK gene copies in the BLBC subtype (p<0.001)." (PMID 35749404, 2022). "In vitro function experiments demonstrated that MELK knockdown or miR-145-3p mimics partially rescued the stimulative effects of PCDHB17P overexpression on breast cancer cells migration, invasion, and angiogenesis." (PMID 34350110, 2021). "Five hub genes, RRM2, TOP2A, PBK, MELK, and NUSAP1, which are associated with breast cancer pathogenesis, are gradually upregulated from NME to DCIS and then downregulated in IDC." (PMID 34094915, 2021). "This study shows that hub genes associated with breast cancer pathogenesis, namely RRM2, TOP2A, PBK, MELK, and NUSAP1, are gradually upregulated from NME to DCIS and then downregulated in IDC." (PMID 34094915, 2021). "MELK is overexpressed in multiple human cancers, such as colorectal cancer, melanoma, and basal-like breast cancer cells and is a cell cycle-regulated gene regulated by E2F transcription factors." (PMID 34550356, 2021). "MELK is significantly upregulated in many human cancers, including breast cancer, but it exhibits low or undetectable expression in normal organs, except the testis." (PMID 34285339, 2021). "MELK disruption is found to inhibit tumor growth and trigger cell cycle arrest in breast cancer cells." (PMID 33801837, 2021). "Hub genes, namely TOP2A, MELK, PBK, NUSAP1, and RRM2, are closely associated with the occurrence and pathogenesis of breast cancer." (PMID 34094915, 2021).
breast carcinoma (continued). "In summary, the present study firstly revealed that PCDHB17P was upregulated in breast cancer tissues and cell lines, MELK mediated PCDHB17P-induced promotion on breast cancer metastasis and angiogenesis by sponging miR-145-3p." (PMID 34350110, 2021). "TCGA database analysis showed that the expression of MELK and miR-145-3p was negatively correlated in Breast cancer tissues." (PMID 34350110, 2021). "Recently OTS167 has been shown to inhibit the MELK-dependent phosphorylation of eIF4B in human breast cancer cell lines, which resulted in downregulation of anti-apoptotic factor myeloid cell leukemia 1 (MCL-1) expression." (PMID 33658483, 2021). "GSEA based on the breast cancer TCGA datasets showed MELK expression was related to metastasis and angiogenesis." (PMID 34350110, 2021). "In this study, we revealed that MELK was expressed at high levels in breast cancer tissues, which was consistent with previous researches." (PMID 34350110, 2021). "MELK level was increased in breast cancer samples compared with that in the normal tissues, as confirmed by the TCGA database and frozen clinical samples (–J)." (PMID 34350110, 2021). "For this purpose, we engineered doxycycline-inducible shRNA vectors targeting MELK, which we transduced into MCF10A, BT-20, and MDA-MB-231 cells as the latter two breast cancer cell lines overexpress MELK with MCF10A cells as a control." (PMID 34550356, 2021). "Collectively, despite strong controversy, these findings suggest that MELK is necessary for the growth of cancer cells, especially breast cancer cells." (PMID 34285339, 2021). "The upregulation of MELK has been detected in many kinds of tumors consisting of gastric cancer, breast cancer, glioblastomas, colorectal cancer, prostate cancer, and melanoma." (PMID 32391256, 2020). "In this study, we sought to determine the molecular mechanism by which MELK is upregulated in TNBC breast cancers." (PMID 31909186, 2020). "Taken together, these data suggest a confused role of MELK in basal-like breast cancer and further study is required." (PMID 31428132, 2019). "We previously reported that OTS167, a putative MELK inhibitor in clinical trials, kills breast cancer cells in a MELK-independent manner." (PMID 29417930, 2018). "High MELK expression predicts a poor prognosis of many cancer types, including but not limited to breast cancer, astrocytoma and glioblastoma." (PMID 29416794, 2018). "The high expression of MELK is correlated aggressive subtypes and poor prognosis of breast cancer and poorly differentiated phenotypes in human astrocytoma and prostate cancers." (PMID 29783958, 2018). "For example, MELK has been characterized as an oncogenic kinase essential for basal-like breast cancer (BBC) via a kinome-wide screening, integrative analysis with multiple GE datasets, and further in vitro and in vivo experiments." (PMID 28327601, 2017). "We further used the Breast Cancer Gene-Expression Miner to evaluate MELK mRNA levels in clinical samples." (PMID 28235006, 2017). "In particular, MELK has been identified as a key driver of basal-type breast cancer, suggesting a novel therapeutic approach to treat this disease." (PMID 28337968, 2017).